ERBB3 (erb-b2 receptor tyrosine kinase 3)
Diseases named in the same sentence as ERBB3 in open-access papers (continued):
Sharing a sentence is not in itself a finding about the gene and the disease.
glioblastoma (19 papers, 2010 to 2025). The most malignant astrocytic tumor (WHO grade IV). "The 50 kDa variant of ErbB3 found in glioblastoma nucleoli also interacts with key ribosome biogenesis factors, such as the upstream binding factor (UBF)." (PMID 40362410, 2025). "Silencing of ErbB3 affects cell viability thus underlining the role of nucleolar ErbB3 as a potential target in glioblastoma." (PMID 35255831, 2022). "We further explored the ErbB3 nucleolar function in glioblastoma describing, for the first time, the presence of the 50 kDa variant of ErbB3 receptor in the nucleolus of glioblastoma cells." (PMID 35255831, 2022). "The second variant, a 50 kDa ErbB3, colocalizes with fibrillarin in the nucleoli of various tumor cell lines and primary glioblastoma cells and relocates from the nucleolus to the cytoplasm, when the levels of the NRG-1 ligand increase, promoting pre-rRNA synthesis." (PMID 40362410, 2025). "Overexpression of ERBB3 has been shown to be associated with short survival of primary glioblastoma and is more frequent (up to 62%) in recurrent gliomas, suggesting that high ERBB3 activity may be involved with tumor aggressiveness and resistance to chemotherapy." (PMID 39767683, 2024). "Our work goes in the same direction and our findings support nucleolar ErbB3 as a new player in glioblastoma cancer cells." (PMID 35255831, 2022). "Immunostainings were performed in different glioblastoma cell lines such as the U-87MG, known to express ErbB3, the U-251MG and the U-373MG." (PMID 35255831, 2022). "The expression of the 50 kDa ErbB3 was also verified by western blot in cellular extracts obtained from glioblastoma primary cell cultures and from U-251MG, A-172 and U-373MG cell lines." (PMID 35255831, 2022). "This nuclear/cytoplasm traffic of ErbB3 observed in vitro was also confirmed in ex-vivo in glioblastoma primary cells." (PMID 35255831, 2022). "Although there is an extensive literature concerning the role of ErbB1 in glioblastoma, few studies have investigated the contribution to glioblastoma development by the other members of the ErbB family, such as ErbB3." (PMID 35255831, 2022). "The nucleolar localization of ErbB3 was also investigated in glioblastoma primary cells obtained from biopsies of affected patients." (PMID 35255831, 2022). "The Erbb3, Gli1 and Mdm2 genes are all present in this region, and their amplification is known to have effects in human glioblastoma." (PMID 33435218, 2021). "Receptor tyrosine-protein kinase ErbB-3 (ERBB3) is known to mediate glioblastoma cancer stem-like cell resistance to EGFR inhibition." (PMID 30626092, 2019). "The overexpression of c-erbB3 and c-erbB4 is in accordance with our previous study on glioblastomas as well as with others." (PMID 20331873, 2010). "For lower grade glioma, ERBB3 showed marked underexpression in most glioblastomas." (PMID 37968615, 2023). "When the concentration of NRG1 increases, (overexpressed in high grade glioblastoma), the ErbB3/C23 could be released from the complex and moves to the cytoplasm, with positive effect on cell proliferation." (PMID 35255831, 2022). "Our finding shows a significant reduction of cells in S phase after ErbB3 silencing, suggesting this approach as a new potential therapeutic treatment alone or in combination with other therapies, to counteract tumor progression in glioblastoma." (PMID 35255831, 2022). "Our findings support the hypothesis for the existence, of an ErbB3 alternative pathway controlling cell proliferation of glioblastoma cells that opens new perspectives to investigate therapeutic approaches aimed to modulate ErbB3 in glioblastoma." (PMID 35255831, 2022). "Nucleolin has been shown to be overexpressed in glioblastoma where its cytoplasmic localization increases proportionally to the tumor grade, thus the interaction between ErbB3 and C23 could have a functional related to tumor progression." (PMID 35255831, 2022).
glioblastoma (continued). "This scenario might explain the nucleolar localization of ErbB3 in primary cells of glioblastoma and the partial nucleolar localization observed in patient biopsies." (PMID 35255831, 2022). "Therefore, targeting ERBB receptor family members like EGFR, ERBB2 or ERBB3 alone or in combination with other epithelial markers such as EpCAM, will provide opportunities to detect and isolate CTCs that represent primary tumors of ovarian and glioblastoma." (PMID 29321816, 2017). "Here we provide evidence that one of such mechanisms can be miRNA‐483‐3p overexpression, which mainly results in upregulated expression and signaling activity of ERBB3, a prominent regulator of stem‐like cells in CRC and in glioblastoma, where ERBB3 specifically sustains the PI3K/AKT axis." (PMID 36862005, 2023). "We found that EGFR and ERBB2 mRNA expression levels were higher in glioblastoma (GBM, WHO IV) than in other grades (WHO grade II & III), while the ERBB3 and ERBB4 mRNA expression levels were the opposite." (PMID 33892666, 2021).
glioma (18 papers, 2011 to 2024). A benign or malignant brain and spinal cord tumor that arises from glial cells (astrocytes, oligodendrocytes, ependymal cells). "EGFR and ERBB2 were notably downregulated in IDH mutant gliomas, while ERBB3 and ERBB4 were upregulated, which was associated with a poor prognosis." (PMID 33892666, 2021). "In summary, the mRNA levels of EGFR and ERBB2 were higher in advanced and poorly differentiated gliomas; however, the mRNA levels of ERBB3 and ERBB4 were lower in advanced and poorly differentiated gliomas." (PMID 33892666, 2021). "A paired overexpression of ErbB3 and Sox10 has been observed in pilocytic astrocytoma (PA) a common glioma of childhood, which verifies their network connection found in the current study." (PMID 23835063, 2013). "In 2008, Contessa and colleagues reported that inhibition of N-linked glycosylation reduced RTK (i.e. EGFR, ErbB2, ErbB3 and IGF-IR) signaling through AKT and radiosensitized tumor cells in glioma and pancreatic adenocarcinoma cell lines." (PMID 22192458, 2011). "According to the Stupp protocol and metronomic dose of the temozolomide treatment, the mutated genes related to the second relapse of patients with high-grade glioma were PIK3C2B, KIT, ERBB3, and MLH1." (PMID 39767683, 2024). "The expression of ERBB3 and ERBB4 mRNA in gliomas was notably negatively correlated with the level of B cell infiltration (ERBB3, r = − 0.08882, p < 0.0201, ERBB4, r = − 0.1591, p < 0.001)." (PMID 33892666, 2021). "Analysis of the TCGA data and the CGGA RNA-seq data found that ERBB3 and ERBB4 were notably increased in IDH mutant gliomas, and the same result was found in the CGGA RNA-seq datasets." (PMID 33892666, 2021). "The mRNA expression of ERBB3 and ERBB4 in gliomas was notably positively correlated with the level of CD4+ T cell infiltration (ERBB3, r = 0.1200, p = 0.0016, ERBB4, r = 0.09663, p = 0.0114)." (PMID 33892666, 2021). "Despite increased DNA hypermethylation, the mean ERBB3 abundance and phosphorylation were statistically increased in IDH-mutant gliomas." (PMID 27852048, 2017). "We observed increased DNA methylation in EGFR, ERBB2, ERBB3, FGFR3, and PDGFRB in IDH-mutant gliomas as the mean methylation of each gene was statistically greater than that of IDH-wildtype." (PMID 27852048, 2017). "According the previous results, ERBB-2 and ERBB-3 mRNAs were detected only in a few high-grade gliomas, while ERBB-4 expression was most pronounced in low-grade gliomas." (PMID 24986561, 2014). "Next-generation sequencing (NGS) of three cases identified mutations in a few genes known to be altered in low-grade gliomas, (e.g., BCOR, BCORL1, ERBB3, MYB, and ATM), but no recurrent mutations were seen." (PMID 31114608, 2019). "Therefore, we conclude that increased ERBB3 abundance and PIK3R1 expression and decreased ERBB2, FGFR3, and AKT2 expression may explain the improved LGG patient survival in IDH-mutant gliomas compared with IDH-wildtype gliomas." (PMID 27852048, 2017).
diabetes (15 papers, 2015 to 2025). "In the progression from AAB positivity to clinical diabetes, ERBB3 showed a significant association in this subgroup (p = 0.00068)." (PMID 35812428, 2022). "Lower ERBB3 was associated with older age, male sex, marginally lower BMI, higher prevalence of DM, prior MI and HF, and greater use of a range of cardiovascular and diabetes medications." (PMID 39180332, 2024). "Additionally, some studies have indicated that the gene polymorphism of ERBB3 is closely associated with diabetes." (PMID 36551281, 2022). "Interestingly, a recent paper from the Belgian Diabetes Registry described that ERBB3/IKZF4 risk alleles increased the progression from single to multiple AABs, but this was seen only in female relatives." (PMID 35812428, 2022). "ERBB3 encodes ERB-b2 receptor tyrosine kinase 3, and gene polymorphism and multi-omics studies have found that ERBB3 is related to diabetes and is a potential DR therapeutic target." (PMID 41340073, 2025). "By assessing myocardial transcriptomic hits in their circulating protein form, we validated lower ERBB3 and higher HSPA2 in people with diabetes and found these to be associated with LV dysfunction, incident HF, and cardiovascular mortality." (PMID 39180332, 2024). "This work found diabetes is characterized by lower Erbb3 and higher Hspa2 mRNA expression in myocardium, with directionally concordant differences in their plasma protein concentration." (PMID 39180332, 2024). "In the whole UKB plasma proteomics cohort, including participants without diabetes, we found lower plasma ERBB3 and higher HSPA2 to be associated with impaired LV contractility, incident HF, and cardiovascular mortality." (PMID 39180332, 2024). "Notably, the expression of ErbB3 itself increases during fasting and diabetes, a phenomenon that can be reversed by insulin administration, indicating that ErbB3 expression is under direct regulation of hormonal or nutrient status." (PMID 32372975, 2020). "In patients with BC that develop diabetes, neuregulin 1 (NRG1) and epidermal growth factor receptor 3 (ERBB3) overexpression exacerbate tumor growth and progression." (PMID 37389721, 2023). "We selected SNPs rs2292239 and rs1701704, located near ERBB3/IKZF4, to investigate this in a cohort of autoAb+ FDRs followed by the Belgian Diabetes Registry (BDR)." (PMID 34448034, 2021). "The effect of ERBB3/IKZF4 genotypes and sex, on the progression of single autoantibody positivity to multiple autoantibody positivity and from multiple autoantibody positivity to diabetes, was studied by Kaplan–Meier analysis and multivariate Cox regression." (PMID 34448034, 2021). "Similarly, the phosphorylation ratio of ERBB2 is higher and that of ERBB3 and ERBB4 is lower in mice with diabetes compared with controls." (PMID 28496106, 2017).
head and neck cancer (14 papers, 2008 to 2025). A primary or metastatic malignant neoplasm affecting the head and neck. "This phase II, Simon 2-stage, multicenter study evaluated the efficacy of the combination of CDX-3379 and cetuximab, monoclonal antibodies against ErbB3 and EGFR, respectively, in patients with recurrent/metastatic, HPV-negative, cetuximab-resistant head and neck cancer." (PMID 35625959, 2022).
lymph node metastasis (14 papers, 1992 to 2025). "Moreover, the ROC analysis indicated that the AOD values of ERBB3 protein immunohistochemical positive staining could serve as a promising diagnostic biomarker for determining the occurrence of lymph node metastasis in THCA cases (AUC=0.89, 95%CI 0.73-1.00)." (PMID 38144565, 2023). "We also found a significant association between patients with lymph node metastasis and overexpression of BMP7 (47.4%, P=0.005), CALD1 (42.1%, P=0.020), CDH1 (52.6%, P=0.001), COL3A1 (42.1%, P=0.020), EGFR (47.4%, P=0.005), ERBB3 (57.9%, P=0.000), PLEK2 (47.4%, P=0.024), and TCF4 (52.6%, P=0.001)." (PMID 34527572, 2021). "High expression of ERBB3 is positively associated with the presence of lymph node metastases, but there was no demonstrable relationship with patient survival in this series." (PMID 1333787, 1992). "Notably, there exists limited research on ERBB3 in THCA, and at present, no studies have reported the potential biological functions of ERBB3 in THCA lymph node metastasis." (PMID 38144565, 2023).
metastatic tumors (13 papers, 2011 to 2025). "Three new somatic mutations, including ERBB3, DNMT3A and NOTCH1 mutations were detected in the metastatic tumor." (PMID 30850667, 2019). "However, only ErbB2 and MET levels were found to be statistically different between samples from primary and metastatic tumor tissue and, along with ErbB3, they exhibited the highest variation of expression values." (PMID 29719603, 2018).
schizophrenia (13 papers, 2009 to 2024). A major psychotic disorder characterized by abnormalities in the perception or expression of reality. "However, the genetic association between erbB3 SNPs and schizophrenia remains controversial." (PMID 23408472, 2013). "Three schizophrenia-unique genes related to glial cell differentiation were identified: ERBB3, PTPRZ1, and SOX10." (PMID 32398742, 2020). "In human prefrontal cortex, microarray analyses revealed that the level of ErbB3 was significantly reduced in schizophrenia subjects relative to a normal cohort." (PMID 26029044, 2015). "It has been reported that ErbB3 is associated with schizophrenia in a Caucasian population, and thus there is a possibility that neuroglycan C-ErbB3 signaling is involved in the pathophysiology of schizophrenia." (PMID 25852466, 2015). "A recent study revealed that signals from ErbB2:ErbB3 complexes in the neocortex regulate the expression of disrupted schizophrenia 1 (DISC1), which has been implicated in the genetics of schizophrenia." (PMID 23408472, 2013). "In order to investigate a relationship between ERBB3 gene and schizophrenia in the Chinese population, case-control and family-based studies were carried out in 470 cases matched by controls, and in 532 family trios." (PMID 21637446, 2009). "ERBB3 (v-erb-b2 erythroblastic leukemia viral oncogene homolog 3), encoding a receptor of neuregulin-1 (NRG1), has been considered a functional candidate gene for schizophrenia susceptibility." (PMID 21637446, 2009). "Genes enriched in myelin-forming oligodendrocytes were also transcriptionally downregulated in the PFC in schizophrenia subjects: myelin and lymphocyte protein (MAL), 2′,3′-cyclic nuclei 3′-phosphodiestarase, myelin-associated protein (MAG), transferrin, gelsolin, HER3 (ErbB3)." (PMID 36833173, 2023). "Of these pathways, schizophrenia appears to have to strongest link to the Nrg/ErbB pathway, and SNPs in several of the genes encoding Nrg (NRG1, NRG2, NRG3, and NRG6) and all of the genes encoding ErbB receptors (EGFR, ERBB2, ERBB3, and ERBB4) have been linked to schizophrenia." (PMID 30618607, 2018). "Neuregulin 1-ErbB receptor signaling appears to play a critical role in the ontogeny of psychiatric disorders and this hypothesis has been supported by the identification of altered expression levels and/or function of NRG1, ErbB3, and ErbB4 in patients with schizophrenia." (PMID 26029044, 2015). "Thus, several schizophrenia studies have focused on ErbB3 function." (PMID 23408472, 2013). "However, studies in samples from the Japanese population did not reveal any association between ERBB3 polymorphisms and schizophrenia." (PMID 21637446, 2009). "MiR-143 is a critical miRNA involved in schizophrenia development by targeting some major genes contributing to the onset of schizophrenia, including ERK5, ERBB3, HK2, and PKCε." (PMID 39058106, 2024). "The crosstalk of PID candidate pathway for schizophrenia between hedgehog signaling pathway and other cancer-related pathways such as LKB1 signaling events, Aurora signaling pathway, ErbB2/ErbB3 signaling pathway and TNF alpha/NFkB signaling pathway." (PMID 25522158, 2014). "Seven genes, APP, ERBB3, FEZ1, HSPA2, SERPINI1, SOX10 and SYN2, display altered expression in studies of schizophrenia or bipolar disorder." (PMID 19300510, 2009). "Moreover, to clarify the role of ERbB3 in a low mood state, new studies on MDD with larger samples and in cohorts of patients with different psychiatric disorders in a depressive state, such as post-traumatic stress disorder (PTSD) or schizophrenia, are necessary." (PMID 22989054, 2012).
gastric adenocarcinoma (12 papers, 2015 to 2025). "Collectively, these observations strongly support the involvement of ERBB3 in the ferroptosis pathway, including its potential implications in gastric adenocarcinoma." (PMID 40846695, 2025). "Of these, 8 regions contained previously characterized amplified oncogenes: GATA4, CCND1, CDK6, MDM2, EGFR, MCL1, ERBB3 and MYB; this is the first report of significant and nearly isolated MYB amplification in gastric adenocarcinoma." (PMID 28426752, 2017). "For example, ERBB3, which is an established cancer gene, is identified as such by RVdriver in breast invasive carcinomas, stomach adenocarcinomas, and uterine corpus endometrial carcinomas, but not by DNA-based tools in any of those instances." (PMID 40514689, 2025).
endometrial cancer (11 papers, 2008 to 2026). Primary or metastatic malignant neoplasm involving the endometrium (mucous membrane that lines the endometrial cavity). "In the present study, using a TCGA dataset, we found that ERBB2 and ERBB3 were overexpressed in breast and endometrial cancer tissues compared with normal counterparts." (PMID 35740327, 2022). "In our study, although ErbB-2 was upregulated in endometrial cancer, ErbB-2 and ErbB-3 were downregulated in patients with vulvar cancer." (PMID 26559525, 2015). "ERBB3 expression was evaluated in public datasets and examined in endometrial cancer cells." (PMID 42279348, 2026).
gallbladder cancer (11 papers, 2018 to 2025). "Preclinical studies have revealed that genomic ERBB2/ERBB3 mutations promote PD-L1–mediated immune escape in gallbladder cancer through inhibiting the ability of tumor-reactive T cells and attenuating the release of Interferon (IFN-γ) and Interleukin-2 (IL-2)." (PMID 37681031, 2023). "EGFR family genes including EGFR, ERBB2 (HER2), ERBB3 (HER3) were the most activating gene in gallbladder cancer while EPHA2 mutation was found frequently in intrahepatic CCA (iCCA)." (PMID 32093644, 2020). "Using whole exome sequencing, ERBB3 mutations have been reported in colon, gastric, and gallbladder cancers." (PMID 30057548, 2018). "Preclinical study has shown that ERBB2/ERBB3 mutations could promote PD-L1–mediated immune escape in gallbladder cancer." (PMID 37681031, 2023). "Extrahepatic cholangiocarcinoma more commonly involves genetic abnormalities in PKA and HER2, while gallbladder cancer frequently harbors EGFR, HER2, and ERBB3 alterations." (PMID 40688855, 2025).
squamous cell carcinoma (11 papers, 2011 to 2025). A carcinoma arising from squamous epithelial cells. "Conversely, the expression of ERBB3, MSLN, and MUC-1 was markedly elevated in adenocarcinoma relative to squamous cell carcinoma." (PMID 40046734, 2025). "ERBB3, MSLN, and MUC-1 expression was markedly elevated in adenocarcinoma relative to squamous cell carcinoma." (PMID 40046734, 2025).